FABP5 (fatty acid binding protein 5)
Diseases named in the same sentence as FABP5 in open-access papers (continued):
Sharing a sentence is not in itself a finding about the gene and the disease.
mesothelioma (1 paper, 2025). A usually malignant and aggressive neoplasm of the mesothelium which is often associated with exposure to asbestos. "The identified overexpression of the fatty acid transporter FABP5 in mesothelioma cells further supports this association, as FABP5 is known to play a crucial role in fatty acid uptake and metabolism in various cancers." (PMID 40016284, 2025). "We questioned ourselves: could the expression of FABP5 be linked with NF-κB activity in mesothelioma cells?" (PMID 40016284, 2025). "Additionally, targeting FABP5 and its associated metabolic pathways may improve treatment outcomes for mesothelioma patients, particularly those resistant to current therapeutic approaches." (PMID 40016284, 2025). "The reduction in proliferation rates and the induction of apoptosis in mesothelioma cells upon FABP5 silencing highlight the potential of FABP5 as a promising therapeutic target." (PMID 40016284, 2025). "The therapeutic implications of targeting FABP5 in mesothelioma are underscored by the observed effects of FABP5 silencing on cell dynamics, metabolism, and NF-κB activity." (PMID 40016284, 2025). "Strikingly, FABP5 silencing led to a significant reduction in NF-κB activity in mesothelioma cell lines, aligning the levels with those observed in normal mesothelial cells." (PMID 40016284, 2025). "Utilizing the NF-κB-Luciferase reporter system, we transfected mesothelioma cell lines with FABP5 siRNA or control scrambled siRNA." (PMID 40016284, 2025). "The observed alterations in proliferation, apoptosis, and metabolism upon FABP5 silencing highlight its significance as a prospective therapeutic target in the pursuit of novel strategies against mesothelioma." (PMID 40016284, 2025). "Based on our earlier identification of upregulated NF-κB dependent cytokines in mesothelioma, we explored the effect of FABP5 silencing on their expression." (PMID 40016284, 2025). "Importantly, our findings establish a correlation between NF-κB dysregulation and the overexpression of FABP5, shedding light on a potential molecular link between lipid metabolism and inflammation in mesothelioma." (PMID 40016284, 2025). "Notably, we identify FABP5 as a key player in driving metabolic alterations and inflammation through NF-κB dysregulation in mesothelioma cells, distinguishing them from normal mesothelial cells." (PMID 40016284, 2025). "Further, we found FABP5 silencing triggered notable metabolic shifts in mesothelioma cells." (PMID 40016284, 2025). "However, a notable distinction unfolded with the increased and specific expression of FABP5 in mesothelioma cell lines, presenting a potential contributor to the observed increase in free fatty acid uptake." (PMID 40016284, 2025). "Additionally, FABP5 silencing resulted in a decrease in IKK activity in mesothelioma cell lines." (PMID 40016284, 2025). "Remarkably, FABP5 silencing induced a significant increase in apoptosis, as evidenced by Annexin-V assay, in both mesothelioma cell lines IstMes2 and MPP89, while apoptosis levels in normal mesothelial cells remained unaltered." (PMID 40016284, 2025).
metastatic cancer (1 paper, 2012). A carcinoma which has spread from the original site of growth to another anatomic site. "FABP5 gene is overexpressed in both primary and metastatic cancer." (PMID 22811706, 2012).
metastatic prostate carcinoma (1 paper, 2021). A carcinoma that arises from the prostate gland and has spread to other anatomic sites. "For instance, FABP5 is a critical driving factor of metastatic prostate carcinoma." (PMID 34249967, 2021).
metastatic tumors (1 paper, 2014). "Mounting evidence has demonstrated that the expression level of FABP5 is low in low grade tumors and highly upregulated as the progression of the disease manifests to aggressive, metastatic tumors, clarifying the importance of a rational drug design targeting FABP5." (PMID 25260874, 2014).
morbid obesity (1 paper, 2018). An excess of body weight, normally defined as an individual with a body mass index greater than 35 or a body weight greater than one hundred percent of ideal body weight. "Nonetheless, the expression of FABP5 increased significantly in VAT of patients with morbid obesity compared to their SAT level (+36%, P < 0.05)." (PMID 29335416, 2018).
mycosis fungoides (1 paper, 2024). Classical mycosis fungoides is the most common type of mycosis fungoides (MF), a form of cutaneous T-cell lymphoma, and is characterized by slow progression from patches to more infiltrated plaques and eventually to tumors. "Similarly, mycosis fungoides manifests elevated expression levels of FABP5, S100A8, and SOD2." (PMID 38596682, 2024).
nevus (1 paper, 2020). Nevus (or naevus, plural nevi or naevi, from nævus, Latin for "birthmark") is the medical term for sharply circumscribed[1] and chronic lesions of the skin or mucosa. "Next, to validate differential expressions of six prognostic hub genes between CM tissues and nevus tissues, we performed IHC analysis and found significantly elevated FABP5, IVL, KRT6A, KRT15, KRT16, and TIMP2 protein expressions in the CM than in the nevus tissues." (PMID 32934956, 2020). "It suggested that significantly elevated FABP5, IVL, KRT6A, KRT15, KRT16, and TIMP2 proteins expressed in the CM than in the nevus tissues." (PMID 32934956, 2020).
oligodendroglioma (1 paper, 2022). A well-differentiated (WHO grade II), diffusely infiltrating neuroglial tumor, typically located in the cerebral hemispheres. "Indeed, in a human oligodendroglioma cell line, treatment with psychosine caused the mislocalization of fatty acid binding protein 5 (FABP5) to the mitochondria, the formation of mitochondrial pores, and reduced levels of mitochondrial DNA." (PMID 36003149, 2022).
osteoarthritis (1 paper, 2025). A noninflammatory degenerative joint disease occurring chiefly in older persons, characterized by degeneration of the articular cartilage, hypertrophy of bone at the margins and changes in the synovial membrane. "Research has shown that inhibition or genetic knockout of FABP5 has anti‐nociceptive effects in several models of pain, including inflammatory pain, osteoarthritis and chronic constriction injury." (PMID 39188040, 2025). "For example, FABP5 inhibition or knockdown produces CB1‐dependent analgesia in inflammatory pain, osteoarthritis and chronic constriction injury." (PMID 39188040, 2025).
ovarian serous adenocarcinoma (1 paper, 2025). An adenocarcinoma that arises from the ovary and is characterized by the presence of malignant epithelial cells that, in well differentiated tumors, resemble the epithelium of the fallopian tube or, in poorly differentiated tumors, show anaplastic features and marked nuclear atypia. "The results revealed that FA metabolism regulators including FABP4, FABP5, and PPARγ are involved in biological aspects in two EOC cell lines, AMOC-2 cells established from ovarian serous adenocarcinoma (OSC) and ES2 cells established from OCCC." (PMID 40429934, 2025).
pancreatic neuroendocrine tumor (1 paper, 2025). Pancreatic endocrine tumor, also known as pancreatic neuroendocrine tumor (PNET), describes a group of endocrine tumors originating in the pancreas that are usually indolent and benign, but may have the potential to be malignant. "Fatty acid-binding protein 5 regulates the expression of FASN through the ubiquitin–proteasome pathway, activates the WNT/β-catenin signaling pathway, and modulates lipid metabolism to promote the progression of pancreatic neuroendocrine tumors." (PMID 40764609, 2025).
pleural mesothelioma (1 paper, 2025). A neoplasm that arises from the mesothelial cells of the pleura. "Pleural mesothelioma (PM) exhibits altered lipid metabolism and NFκB dysregulation, driven by FABP5, promoting tumor growth and inflammation." (PMID 40016284, 2025).
pneumonia (1 paper, 2019). An acute, acute and chronic, or chronic inflammation focally or diffusely affecting the lung parenchyma, caused by an infection in one or both of the lungs (by bacteria, viruses, fungi, or mycoplasma.). "Furthermore, FABP5 mRNA expression was further decreased in COPD patients who reported flare-up and pneumonia episodes within the last 12 months." (PMID 30877402, 2019).
pterygium (1 paper, 2025). A wedge-shaped fibrovascular lesion arising from the bulbar conjunctiva and extending to the cornea. "FABP5 mRNA expression was significantly higher in pterygium IC and corneal epithelial samples, than in controls (p = 0.007; p = 0.014), whereas its expression remained unchanged in other groups." (PMID 40094891, 2025). "KRT13 mRNA expression was significantly higher in EBMD, SND, and pterygium (p ≤ 0.018), and FABP5 was increased in pterygium samples (p = 0.007)." (PMID 40094891, 2025). "FABP5 mRNA expression was significantly higher in pterygium IC samples than in controls (p = 0.007)." (PMID 40094891, 2025). "ALDHA1 mRNA expression was significantly lower (p < 0.0001), and FABP5 mRNA expression was significantly higher (p = 0.014) in pterygium samples than in controls." (PMID 40094891, 2025). "In addition, there is a dysregulation of markers of the retinoic acid signaling pathway, such as ADH1A1 and FABP5, in the corneal epithelium of pterygium subjects." (PMID 40094891, 2025). "In addition, there is a deregulation of markers of the retinoic acid signaling pathway, such as ADH1A1 and FABP5 in the corneal epithelium of pterygium subjects." (PMID 40094891, 2025). "In addition, interestingly, there was an increased FABP5 mRNA expression without an increased FABP5 protein expression, parallel to a decreased PAX6 and DSG1 expression in conjunctival IC samples and in corneal epithelium of pterygium patients." (PMID 40094891, 2025).
pulmonary hypertension (1 paper, 2024). Increased pressure within the pulmonary circulation due to lung or heart disorder. "It was also previously shown that inhibiting FABP5 expression in mice abrogates pulmonary artery remodeling and improves heart function in left heart disease-associated pulmonary hypertension, and silencing FABP5 attenuates the TGF-β1-induced fibrosis response in cultured PAFs43." (PMID 38830933, 2024).
renal carcinoma (1 paper, 2021). A carcinoma arising from the epithelium of the renal parenchyma or the renal pelvis. "FABP5 may elevate PI3K/AKT-mediated proliferation of renal carcinoma cells." (PMID 34249967, 2021).
renal dysfunction (1 paper, 2020). "There are distinct independent associations of FABP4 level with renal dysfunction, adiposity and high triglycerides level and there is a distinct association of FABP5 level with a low HDL level." (PMID 33071982, 2020).
respiratory infections (1 paper, 2017). "We have recently identified Fatty Acid Binding Protein 5 (FABP5) as an important anti-inflammatory player during respiratory infections." (PMID 28542209, 2017). "We have previously identified Fatty Acid Binding Protein 5 (FABP5) as an important anti-inflammatory player during respiratory infections and showed that overexpression of FABP5 in primary airway epithelial cells protects against bacterial infection and inflammation." (PMID 28542209, 2017).
Sepsis (1 paper, 2024). Sepsis is defined as life-threatening organ dysfunction caused by a dysregulated host response to infection. "Similarly, lipid-regulating enzymes ANXA1, S100A8, and FABP5 are co-regulated in a network with ApoE and APP in response to sepsis." (PMID 38653992, 2024).
stomach adenocarcinoma (1 paper, 2022). "According to the GEPIA and UALCAN databases, FABP4 expression was significantly reduced in stomach adenocarcinoma (STAD) tissues, but Western blot results revealed significantly high expression of FABP4 and Fatty Acid Binding Protein 5 (FABP5) in both GC tissues and GC cells." (PMID 35625633, 2022).
synucleinopathies (1 paper, 2021). "This might indicate a potential role of FABP5 in dopaminergic neuron loss in synucleinopathies." (PMID 34067791, 2021).
tumor (183 papers, 2009 to 2026). "In contrast, overexpression of FABP5 in HCC tissues is associated with poorer tumour differentiation, vascular invasion, advanced TNM stages, and reduced OS and DFS, suggesting its importance as a prognostic marker in HCC." (PMID 41154605, 2025). "FABP5+ tumor-associated macrophages (TAMs) secrete immunosuppressive factors (e.g., IL-10), suppressing CD8+ T cell activity and creating an immunosuppressive microenvironment." (PMID 40717587, 2025). "Subgroup analyses further indicate that FABP5 expression is particularly associated with tumor size in the Chinese patient subgroup, as well as with UICC stage in the subgroup of patients with HCC." (PMID 40178066, 2025). "High FABP5 expression is significantly associated with poor prognosis in pNEN patients, and FABP5 interacts with the PPARγ signaling pathway to enhance tumor cell proliferation and invasion." (PMID 40717587, 2025). "Key genes such as LGALS1, PLA2G5, and FABP5 were upregulated in high-risk patients and enriched in M2-like tumor-associated macrophages." (PMID 41164132, 2025). "On the other hand, FABP4 and FABP5 have been implicated in HCC tumour progression and patient prognosis as reported by several IHC and tissue microarray studies." (PMID 41154605, 2025). "For example, conserved Gpnmb RecAM genes (e.g., Cd63, Fabp5, Lgals3, and Gpnmb) are hallmarks of lipid-associated macrophages found in the tumor microenvironment and chronically inflamed liver and adipose tissue." (PMID 39509324, 2024). "We also explored the potential prognostic values of FABP5, and observed that high FABP5 expression was associated with poor outcomes of patients with most of tumor types." (PMID 36906605, 2023). "We next evaluated the status of surface FABP5 expression and lipid uptake in tumor-associated CD8+ T cells throughout the development of metastatic OvCa." (PMID 38168227, 2023). "In conclusion, our findings demonstrated that NBASP encoded by FAM201A played a tumor-suppressor role in NB carcinogenesis via down-regulating FABP5 to inactivate the MAPK pathway." (PMID 37438449, 2023). "We found that high FABP5 expression was associated with poor OS prognosis by the Kaplan–Meier survival curve and Log-rank test simultaneously in only three tumor types, namely GBM, KIRC and LIHC." (PMID 36906605, 2023). "FABP5 overexpression was observed in many tumor types, and was statistically associated with poor prognosis of several tumor types." (PMID 36906605, 2023). "FABP5 is found up-regulated in the tumor-associated epithelial cell, and it affects tumor growth and progression by binding transported fatty acids and their derivatives, hormones, steroids, carcinogens, and other ligands." (PMID 35445019, 2022). "Overexpression of FABP5 interacts with PPARγ in a coordinated manner to promote malignant progression of tumor including tumor expansion and aggressiveness caused by reduced apoptosis and increased angiogenesis." (PMID 35445019, 2022). "Similar conclusions were derived from a study of patients with uveal melanoma confirming that FABP5 is associated with progression of some types of tumor and can be considered a prognostic marker." (PMID 32856199, 2020). "Furthermore, FABP5 has been identified as associated with monocytic subsets in metastatic melanoma, potentially enhancing tumor migration and survival." (PMID 40717587, 2025). "Notably, FABP5 overexpression is particularly associated with poorer OS in the subgroup of digestive tract malignancies and larger tumor sizes in the subgroup of Chinese patients." (PMID 40178066, 2025). "In tumour-associated macrophages, FABP5 interacts with RTN3 to regulate lipid metabolism." (PMID 41149452, 2025). "The result showed that FABP5 deficiency significantly repressed tumor growth in vivo." (PMID 40391655, 2025).
tumor (continued). "Furthermore, six studies with 790 patients demonstrated that FABP5 expression was more significantly linked to tumor size in patients from China (OR = 1.870, 95% CI = 1.182, 2.959, p = 0.008, I2 = 0.0%) compared to those from other countries." (PMID 40178066, 2025). "One limitation of the current study is the focus on BMDMs as it is possible that FABP5 may regulate distinct transcriptomic, proteomic, and phosphoproteomic responses in tissue resident or tumor-associated macrophages." (PMID 37790380, 2023). "T-C6 was concentrated in a small area in the tumor section, with the overexpression of KRT13 and FABP5 (encoding a fatty acid binding protein found in epidermal cells), which suggested that these spots primarily represented the tumor cells derived from the pancreatic ductal epithelium." (PMID 37124494, 2023). "It has been studied that in GBM, FABP5 expression correlated with an undifferentiated tumor phenotype as a known tumor-associated antigen that could respond to B cell." (PMID 35488886, 2022). "In short-term survivors of GBM (≤6 months), high levels of FABP5 protein were expressed, which was associated with highly proliferating tumor cells and the activation of the v-akt murine thymoma viral oncogene homolog and 3-phosphoinositide-dependent protein kinase-1." (PMID 32214002, 2020). "However, the molecular mechanism underlying the relationship among FABP5, aberrant tumour FA metabolism and LNM in CCa remains elusive." (PMID 32550890, 2020). "Our study connects two hot research areas of tumor, namely, non-coding RNA and FA metabolism together and elucidates a new molecular mechanism underlying the PA induced GC metastasis via FABP5/SP1/UCA1 signaling which contributes to efficient prevention and therapeutic strategies for GC." (PMID 30948929, 2019). "However, deficiency of FABP5 seriously crippled the migration ability of tumor cells, especially after co-culture." (PMID 29914512, 2018). "In this study, we investigated whether FABP5 causes tumor progression and metastasis by way of induction of the EMT pathway." (PMID 28374947, 2017). "In the 243 HCC patients, FABP5‐positive staining (n = 139/243, 57.2%) was associated with poor prognosis and recurrence (P < 0.0001) and showed positive correlation with distant metastasis, tumor size and vascular invasion (P < 0.05)." (PMID 28374947, 2017). "FABP5 loss in TNBC tumor cells inhibited motility and invasion." (PMID 25779666, 2015). "Moreover, loss of FABP5 in TNBC tumor cells inhibits proliferation and invasion in vivo." (PMID 32296646, 2020). "Single-cell analysis of the GSE140228 cohort showed a higher FABP5 positive rate in the tumor edge and ascites, with TAMs the main cell clusters positive for FABP5." (PMID 39871325, 2025). "Long-chain unsaturated FAs released by tumor cells were found to activate PPARγ via FABP5, conferring immunosuppressive properties on TAMs." (PMID 40507339, 2025). "Multiple studies have identified various mechanisms through which FABP5 promotes tumor development, supporting our findings." (PMID 40178066, 2025). "Given the prior evidence linking the anti‐tumor effects of FABP5‐targeting nanoparticles combined with RFA to ferroptosis induction in HCC, this mechanism was further validated using the ferroptosis inhibitor Lipro1." (PMID 40956367, 2025). "While we do not exclude the possibility that host cytokines such as IL-4 synergize with FABP5 signaling, our data highlight the sufficiency of tumor-derived FABP5 to remodel the immune microenvironment, even in the presence of competing endogenous signals." (PMID 41035647, 2025). "FABP5 is significantly overexpressed in oral squamous cell carcinoma (OSCC), and it is linked to tumor progression and invasiveness." (PMID 40426875, 2025). "We constructed a Hepa1-6 tumor model to clarify further the role of FABP5 in regulating MELK-mediated RFA sensitivity in HCC." (PMID 39871325, 2025).